EZH2 (enhancer of zeste 2 polycomb repressive complex 2 subunit)
Diseases named in the same sentence as EZH2 in open-access papers (continued):
Sharing a sentence is not in itself a finding about the gene and the disease.
neuropathic pain (4 papers, 2021 to 2024). Chronic pain caused by damage to nerve fibers. "It was shown that the enhancer of the zeste 2 polycomb repressive complex 2 subunit (EZH2), a histone methyltransferase, facilitated the production of inflammatory mediators in neuropathic pain." (PMID 35682830, 2022). "Thus, the miR-378/EZH2 axis may be a novel target in terms of theranostics for clinical neuropathic pain patients." (PMID 38368171, 2024).
pancreatic adenocarcinoma (4 papers, 2021 to 2024). "Induction of senescence following EZH2 inhibition has previously been described in pancreatic adenocarcinoma resulting in activation of natural killer (NK) cells and T cell immunity." (PMID 39550391, 2024).
parathyroid adenoma (4 papers, 2014 to 2023). "In addition to MEN1 and CCND1, other genes that participate in the development of parathyroid adenoma include those encoding cyclin-dependent kinase inhibitors, along with CTNNB1, EZH2, ZFX, GCM2, and CASR." (PMID 30832348, 2019). "No mutations in genes recently proposed to be implicated in parathyroid adenoma tumorigenesis, such as CTTNB1, EZH2 and POT1, were identified, attesting to the rarity of these candidate genes' potential contributions." (PMID 25594030, 2014).
salivary gland tumors (4 papers, 2015 to 2024). "Despite the limited sample size, EZH2 emerged as a reliable biomarker for malignancy of salivary gland tumors." (PMID 38477804, 2024). "We have investigated the expression of EZH2 by immunohistochemistry on the most common types of salivary gland tumors." (PMID 26377323, 2015). "The purpose of our study is to examine EZH2 expression in a variety of benign and malignant salivary gland tumors, and to investigate if it provides any useful information for their recognition." (PMID 26377323, 2015). "Our result indicates that it would be worth performing such studies along with elucidating the molecular mechanism of EZH2 upregulation in salivary gland tumors." (PMID 26377323, 2015). "EZH2 is a highly sensitive (96.3 %) and specific (100 %) indicator of malignancy in salivary gland tumors." (PMID 26377323, 2015). "The available data, however, suggest that there may be a connection between the behavior of salivary gland tumors and EZH2 expression as well." (PMID 26377323, 2015). "In conclusion, the majority of malignant salivary gland tumors is EZH2 positive." (PMID 26377323, 2015). "Based on this observation EZH2 immunohistochemistry might provide valuable information for the histological examination of salivary gland tumors." (PMID 26377323, 2015). "EZH2 expression in salivary gland tumors, similarly to the tumors of other organs is not characteristic for any tumor type, but is a solid marker of the malignant nature of the tumors." (PMID 26377323, 2015).
small cell carcinoma (4 papers, 2021 to 2023). A neuroendocrine carcinoma composed of small malignant cells which are often said to resemble "oat cells" under the microscope. "EZH2, AURKA and DLL3 are promising targets for which clinically relevant inhibitors are in early phase trials against NEPC and small-cell carcinoma (NCT03480646; NCT04179864; NCT01799278; NCT04702737; NCT04471727)." (PMID 35205640, 2022).
teratoma (4 papers, 2016 to 2023). A non-seminomatous germ cell tumor characterized by the presence of various tissues which correspond to the different germinal layers (endoderm, mesoderm, and ectoderm). "To examine the differentiation potential of these cells, we injected EZH1−/− or EZH2−/− H1 hESCs into immuno-deficient mice and monitored teratoma formation." (PMID 28939884, 2017). "Taken together, the results suggested that the downregulation of Ccnd1 caused by Dnd1-mediated expression of Ezh2 may be crucial for the suppression of teratoma development in germ cells." (PMID 29378702, 2018). "Our results showed a molecular linkage between Dnd1, its target, enhancer of zeste homolog 2 (Ezh2), as well as a target of Ezh2, cyclin D1 (Ccnd1), in the conversion of embryonic germ cells into teratoma-forming cells." (PMID 29378702, 2018). "In Dnd1ter/ter testicular germ cells, the relative expression levels of Ezh2 in comparison to those in the adjacent gonadal somatic cells slightly increased between E12.5 and E14.5, and then gradually decreased by E18.5 in the teratoma-forming cells." (PMID 29378702, 2018). "In addition, the expression of Ezh2 was downregulated in Dnd1ter/ter germ cells at E16.5 and E17.5, and in the teratoma-forming cells at E17.5, when compared to the levels in wild-type germ cells." (PMID 29378702, 2018). "By contrast, EZH2–/– ESCs failed to produce teratomas in two mice and generated a very small mass in one mouse, which consisted of a restricted set of cell types, including immature adipocytes and epithelial cells." (PMID 27926872, 2016). "However, on the basis of H&E staining of the teratoma sections, we did not observe any ectoderm tissue from teratomas formed from EZH1−/− or EZH2−/− H1 cells." (PMID 28939884, 2017). "Taken together, these results demonstrate that EZH2 is not required for the initial phase of hESC differentiation but is required for the robust generation of mature cell types that are produced in the later stages of differentiation in vitro or in teratoma assays." (PMID 27926872, 2016).
Thrombocytopenia (4 papers, 2020 to 2024). A reduction in the number of circulating thrombocytes. "Differential expression of epigenetic modifiers such as EZH2 in patients marked by plasma leakage and/or thrombocytopenia suggests that there is a role for epigenetic regulation in severe manifestations of dengue." (PMID 31954402, 2020).
thymoma (4 papers, 2020 to 2025). A neoplasm arising from the epithelial cells of the thymus. "EZH2 staining in ≥80% of tumor cells was present in most carcinomas and in only one subtype (type B3) of thymoma." (PMID 37190202, 2023). "Type B3 thymomas were excluded from ROC analysis as EZH2 staining overlapped considerably between carcinoma and B3 thymoma." (PMID 37190202, 2023). "All (37/37) thymic carcinomas and 52% (23/44) of thymomas showed EZH2 staining in >10% of tumor cells." (PMID 37190202, 2023). "Although EZH2 is mentioned in the current WHO as useful for distinguishing B3 thymoma and thymic carcinoma, to our knowledge, this conclusion was only supported by the one prior study." (PMID 37190202, 2023). "In their dataset, EZH2 staining in ≥10% of tumor cells had 89% sensitivity and 100% specificity for thymic squamous cell carcinoma versus B3 thymoma." (PMID 37190202, 2023). "Overall, EZH2 staining in ≥80% of tumor cells was 100% specific for thymic carcinoma versus type A thymoma and MNTLS, and 81% sensitive for thymic carcinoma of any subtype." (PMID 37190202, 2023). "The expression of CD5, KIT (CD117), EMA (MUC1), and EZH2 is frequently observed in thymic SCCs (75–85%), but is rarely expressed in thymomas (usually <5%)." (PMID 34069513, 2021). "EZH2 may be a valuable addition to immunohistochemical panels to distinguish thymic carcinomas from thymoma." (PMID 37190202, 2023). "We also caution that EZH2 staining in thymomas showed considerable heterogeneity." (PMID 37190202, 2023). "Whole slide sections of 37 thymic carcinomas, 23 type A thymomas, 13 type B3 thymomas, and 8 micronodular thymomas with lymphoid stroma (MNTLS) were immunostained for EZH2, POU2F3, CD117, CD5, TdT, BAP1, and MTAP." (PMID 37190202, 2023). "The transcription of NTN1 in THYM is negatively regulated by EZH2 (r = −0.4056), suggesting that the low expression of NTN1 in thymoma is related to the occurrence and development of THYM." (PMID 32251318, 2020). "Of these, NEO1 has the strongest correlation (r = − 0.5814), suggesting that EZH2 may alter the expression of NTN1, NEO1, and UNCB-D to promote the occurrence of thymoma." (PMID 41407823, 2025). "We assessed whether immunohistochemistry for two proteins, EZH2 and POU2F3, could distinguish thymic carcinoma and thymoma." (PMID 37190202, 2023). "EZH2 staining using a ≥80% positivity threshold was 100% specific for thymic carcinoma versus type A thymoma and MNTLS but was not useful for the distinction of thymic carcinoma from type B3 thymoma." (PMID 37190202, 2023). "EZH2 and POU2F3 immunohistochemistry may therefore be useful for distinguishing thymic carcinoma from thymoma." (PMID 37190202, 2023). "Fifty-four percent (7/13) of B3 thymomas but none of the type A thymomas or MNTLS showed EZH2 staining in ≥80% of tumor cells." (PMID 37190202, 2023). "EZH2 (≥80% staining) had a sensitivity of 81% for thymic carcinoma and a specificity of 100% for thymic carcinoma versus type A thymoma and MNTLS but had poor specificity (46%) for thymic carcinoma versus B3 thymoma." (PMID 37190202, 2023). "Of the 10 thymomas (including 6 type A and 4 type B3 thymomas) that lacked TdT-positive thymocytes, 5 had EZH2 staining in <10% of tumor cells, which would help to exclude the possibility of carcinoma." (PMID 37190202, 2023). "Moreover, EZH2 negatively regulates NTN1, NEO1, and UNCB-D in thymoma." (PMID 41407823, 2025). "Overall, absent EZH2 staining may be useful for excluding thymic carcinoma, diffuse EZH2 staining may help to exclude type A thymoma and MNTLS, and ≥10% POU2F3 staining has excellent specificity for thymic carcinoma versus thymoma." (PMID 37190202, 2023). "When considering the percent of tumor cells staining as a continuous variable, thymic carcinomas had significantly more diffuse EZH2 staining compared to type A thymoma (p < 0.0001) and MNTLS (p < 0.0001), but not when compared to type B3 thymoma (p = 0.055, Wilcoxon rank sum tests)." (PMID 37190202, 2023).
thymoma (continued). "However, if EZH2 (≥80%) is the only positive stain, B3 thymoma would not be excluded, given the moderate proportion of B3 thymomas (54%) that had EZH2 staining in ≥80% of tumor cells." (PMID 37190202, 2023). "We found that diffuse EZH2 immunoreactivity was highly specific for thymic carcinoma versus type A thymoma and MNTLS but not type B3 thymoma, whereas the absence of EZH2 immunoreactivity could help to exclude carcinoma." (PMID 37190202, 2023). "EZH2 staining in ≥80% of tumor cells may provide evidence against type A thymoma and MNTLS but does not reliably distinguish thymic carcinoma from type B3 thymoma." (PMID 37190202, 2023).
uterine cancer (4 papers, 2016 to 2024). Primary or metastatic malignant neoplasm involving the uterine corpus and/or the cervix. "Given the frequency of ARID1A mutations in patients with clear cell and endometrioid ovarian and uterine cancer, and the prognostic implications of loss of ARID1A expression, it is natural to explore the impact of EZH2 inhibition in these patient subsets." (PMID 29093822, 2017). "However, our focus is on EZH2, as there is strong evidence to suggest that it can be affected by xenoestrogens and dysregulation of EZH2 leads to a variety of cancers, including uterine cancer, as detailed below." (PMID 33732505, 2020).
Uterine leiomyoma (4 papers, 2018 to 2024). The presence of a leiomyoma of the uterus. "We analyzed the expression status and a potential role of EZH2 in the repression of PRICKLE1 in uterine leiomyomas." (PMID 39314474, 2024). "Uterine leiomyomas express increased levels of EZH2 that inversely correlate with the expression of PRICKLE1." (PMID 39314474, 2024). "Further subgroup analysis showed that EZH2 expression was found in 21 of 23 (91.30%) well-differentiated and significancently higher than that in cellular uterine leiomyoma (p < 0.05)." (PMID 30120321, 2018). "In this study, immunohistochemical analysis was performed in 64 specimens, including 32 LMS, 16 uterine leiomyoma and 16 normal myometrial to quantify and localize the expression of EZH2 protein." (PMID 30120321, 2018). "EZH2 mRNA expression in LMS were significantly higher than those in uterine leiomyoma and normal myometrium (p < 0.05)." (PMID 30120321, 2018). "In contrast, uterine leiomyomas induced by genistein have decreased EZH2 andH3K27me3 marks." (PMID 33732505, 2020). "Other epigenetic alterations include methylation and acetylation of the histone tails, with enhancer of zeste homolog 2 (EZH2) and histone deacetylases (HDACs) being the main enzymes involved in these processes related to uterine leiomyomas." (PMID 34445194, 2021). "The expression of EZH2 mRNA in uterine and extra-uterine LMS were higher than those in uterine leiomyoma and normal myometrium (p < 0.05), respectively." (PMID 30120321, 2018). "The data set GSE764 showed the relative expression levels of EZH2 mRNA in uterine LMS (n = 9), extra-uterine LMS (n = 4), uterine leiomyoma (n = 9) and normal myometrium (n = 4) were 2.54, 5.15, 0.64 and 1, respectively." (PMID 30120321, 2018). "In this study, we detected the expression of EZH2 and three other components of PRC2 in 32 LMS, 51 RMS, 16 uterine leiomyoma, 15 rhabdomyoma as well as 31 normal tissues to evaluate the application value of EZH2 in differential diagnosis." (PMID 30120321, 2018). "The data set GSE64763 showed the relative expression levels of EZH2 mRNA in LMS (n = 25), uterine leiomyoma (n = 25) and normal myometrium (n = 28) were 1.56, 1.11 and 1, respectively." (PMID 30120321, 2018). "Totally, EZH2 protein expression was observed in 26 of 32 (81.25%) LMS, whereas none was found in uterine leiomyoma and normal myometrium (p < 0.05)." (PMID 30120321, 2018).
Wilms tumor (4 papers, 2011 to 2022). An embryonal neoplasm characterized by the presence of epithelial, mesenchymal, and blastema components. "EZH2 mRNA was significantly higher in CCSK compared to Wilms tumor and normal kidney, and the EZH2 protein was strongly expressed in more than 90 % of CCSK tumor cells in 9/9 tumors analyzed." (PMID 26848979, 2016). "Whether H3K27me3 is elevated in CTR9-mutated Wilms tumors, and whether CTR9-mutant expressing tumors are sensitive to EZH2 inhibitors, awaits investigation." (PMID 35137163, 2022). "This was in striking contrast to the lack of EZH2 protein expression in Wilms tumor stromal elements, indicating that EZH2 could be explored further as a diagnostic marker and a potential drug target for CCSK." (PMID 26848979, 2016).
abdominal aortic aneurysm (3 papers, 2021 to 2025). Enlargement and ballooning of the vessel that supplies arterial blood to the abdomen, pelvis and legs. "EZH2 is also closely related to the occurrence and development of abdominal aortic aneurysm (AAA) and thoracic aortic aneurysm (TAA)." (PMID 38994197, 2024).
acute respiratory distress syndrome (3 papers, 2021). Progressive and life-threatening pulmonary distress in the absence of an underlying pulmonary condition, usually following major trauma or surgery. "However, the role of EZH2 in acute respiratory distress syndrome (ARDS)-associated fibrosis remains poorly understood." (PMID 34217280, 2021). "It is possible that the inhibition of neutrophil migration resulting from EZH2 inhibition may have a therapeutic role in diseases associated with excess neutrophilic inflammation, such as adult respiratory distress syndrome." (PMID 34464475, 2021). "Compounds targeting EZH2 are likely to impair mucosal immunity; however, they may prove useful for conditions driven by pulmonary neutrophil influx, such as adult respiratory distress syndrome." (PMID 34464475, 2021).
allergic asthma (3 papers, 2016 to 2023). A asthma with a basis in a pathological type I hypersensitivity reaction. "In addition, an in vivo study reported that loss of Ezh2 in CD4+ T cells resulted in enhanced allergic inflammation and progressive accumulation of memory phenotype Th2 cells in an ovalbumin-induced model of allergic asthma." (PMID 28740493, 2017).
Aortic dissection (3 papers, 2018 to 2021). Aortic dissection refers to a tear in the intimal layer of the aorta causing a separation between the intima and the medial layers of the aorta. "Here we report a novel function of EZH2 in regulating autophagic cell death (ACD) of vascular smooth muscle cells (VSMCs) that affect aortic dissection (AD)." (PMID 29416002, 2018). "In addition, EZH2 activation has preventive potential for aortic dissection as its overexpression inhibits autophagic cell death of aortic vascular SMCs." (PMID 34781960, 2021). "For example, our recently published results demonstrated that EZH2 loss of function facilitates autophagic death of VSMCs to aggravate aortic dissection, and we found that LC3, a hall mark of autophagy, is upregulated in the aortic samples of human aortic dissection patients." (PMID 32174799, 2020).
ataxia telangiectasia (3 papers, 2018 to 2023). Ataxia-telangiectasia is the association of severe combined immunodeficiency (affecting mainly the humoral immune response) with progressive cerebellar ataxia. "Consistent with this latter interpretation, in a disease model for ataxia telangiectasia, shRNA knock-down of EZH2 was protective against neurodegeneration." (PMID 30305625, 2018).
atrial fibrillation (3 papers, 2022 to 2023). A disorder characterized by an electrocardiographic finding of a supraventricular arrhythmia characterized by the replacement of consistent P waves by rapid oscillations or fibrillatory waves that vary in size, shape and timing and are accompanied by an irregular ventricular response. "MiR-101a-3p might also prevent the development of atrial fibrillation in rats by targeting EZH2 to inhibit collagen synthesis and atrial fibrosis." (PMID 35954191, 2022). "Both EZH2 inhibitor GSK126 and molecular silencing of EZH2 can block Ang-II-induced atrial fibroblast activation, migration, and ECM production in mice, attenuate Ang-II-induced atrial enlargement and fibrosis, and reduce atrial fibrillation vulnerability." (PMID 35954191, 2022).
atypical teratoid rhabdoid tumor (3 papers, 2021 to 2026). Atypical teratoid rhabdoid tumor (ATRT) is a highly malignant central nervous system (CNS) rhabdoid tumor (RT) found almost exclusively in children. "BACKGROUND: Atypical teratoid/rhabdoid tumors (AT/RT) are aggressive pediatric CNS malignancies characterized by SMARCB1 loss, which leads to the dysregulated expression of Enhancer of Zeste Homolog 2 (EZH2), a key catalytic component of the Polycomb Repressive Complex 2 (PRC2)." (PMID 41915306, 2026). "Inactivating mutations in SMARCB1 confer an oncogenic dependency on EZH2 in atypical teratoid rhabdoid tumors (ATRTs), but the underlying mechanism has not been fully elucidated." (PMID 39472584, 2024).
bile duct carcinoma (3 papers, 2016 to 2021). "Associations have also been reported between EZH2 overexpression and poor prognosis in esophageal, gastric, pancreatic, and bile duct cancers." (PMID 26871294, 2016). "Noticeably, the increased proliferation upon EZH2 inhibition was also observed in human cancer cell lines of other origins, such as colorectal and bile duct carcinoma." (PMID 34845197, 2021). "In gastrointestinal cancers, EZH2 overexpression has been shown in colorectal, esophageal (squamous cell carcinoma), gastric, pancreatic, and bile duct cancers." (PMID 26871294, 2016). "EZH2 can inhibit the expression of miR-34a by mediating the H3K27 methylation and DNA methylation in bile duct carcinoma." (PMID 33718109, 2020).